RAD21 (RAD21 cohesin complex component)
Diseases named in the same sentence as RAD21 in open-access papers (continued):
Sharing a sentence is not in itself a finding about the gene and the disease.
prostate carcinoma (7 papers, 2012 to 2025). A carcinoma that arises from epithelial cells of the prostate gland. "A review of TCGA data presented in cBioportal for breast, lung, and prostate cancers showed that RAD21 expression correlated with GISTIC copy number assessments." (PMID 35227290, 2022). "We confirmed that in MCF7 cells RAD21 binds a putative enhancer for MYC that we termed C SNP, due to its proximity to a SNP associated with colorectal (CRC) and prostate cancer." (PMID 23145106, 2012). "Finally, RAD21 is amplified and over-expressed in prostate cancer, and its expression is correlated with invasion and metastasis in oral squamous cell carcinomas." (PMID 23962039, 2013). "Further ChIP-seq analysis in prostate cancer cell lines indicated multiple positive signals in the EcoRI fragment BE8-9 (chr2: 85778503–86781283) including H3K4me1 and FOXA1 in LNCaP; CTCF and FOXA1 in VCaP, and RAD21 in NCIH660." (PMID 26979803, 2016).
myeloid neoplasm (6 papers, 2015 to 2025). Proliferation of myeloid cells originating from a primitive stem cell. "Together with high‐frequency mutations, we identified rare mutations, including those in SMC3, RAD21, and SH2B3, which were also found in other myeloid neoplasms." (PMID 36916780, 2023). "Mutations in cohesin subunits RAD21, SMC1, SMC3, and STAG2 are seen in several myeloid neoplasms." (PMID 39747661, 2025). "Despite RAD21 and SMC3 TFs belonging to the same cohesin complex involved in DNA damage repair and whose composing genes are frequently mutated in myeloid neoplasms, these regulators are located at different network layers as a result of their different effects on their regulating modules." (PMID 32471360, 2020). "Recurrent mutations and deletions involving multiple components of the mitotic cohesion complex, including STAG2, RAD21, SMC1A and SMC3, were reported in different myeloid neoplasms." (PMID 26317787, 2015).
bladder cancer (5 papers, 2020 to 2024). "In agreement with previous data, our data showed significant upregulation of RAD21 expression in bladder cancer tissues compared to normal." (PMID 37474724, 2023). "It was also reported that RAD21 was overexpressed in bladder cancer tissues, it was proposed that RAD21 overexpression affected the RAD21 co-expressed cell cycle regulatory genes, which in turn affected cell cycle processes and contributed to tumorigenicity." (PMID 37474724, 2023). "Similarly, another study using high-throughput sequencing demonstrated a strong correlation between high levels of RAD21 in bladder cancer tissues and poor prognosis of bladder cancer patients." (PMID 38378967, 2024). "Moreover, in 413 bladder cancer samples (data derived from TCGA), a significantly higher expression level of four genes, RAD21, RAD51, BARD1, and ERBB2, was observed in ERBB-low as compared to ERBB-high tumours." (PMID 39080120, 2024). "Functional validation of the dataset confirmed GATA3, SPT6, and the cohesin complex components SMC1A, and RAD21, as permissive upstream positive regulators of PPARG gene expression in luminal bladder cancer." (PMID 37250326, 2023). "In this current investigation we examined RAD21, RAD50 or/and BARD1 co-expression with different status of ERBB2 expression and assessed their prognostic and clinical significance in bladder cancer." (PMID 37474724, 2023). "This study evaluates the biological and prognostic significance of RAD21, RAD50 and BARD1 (homologous recombination biomarkers) mRNA levels with ERBB2 low and high expression to explore their impact on bladder cancer patient survival and cancer aggressiveness." (PMID 37474724, 2023). "The expression of ERBB2, RAD21, RAD50 and BARD1 mRNA levels was assessed in The Cancer Genome Atlas (TCGA) bladder cancer dataset along with four validation cohorts." (PMID 37474724, 2023). "Importantly, here we showed that high RAD21, RAD50 or BARD1 mRNA expression in bladder cancer patients with low-ERBB2 exhibit poor survival." (PMID 37474724, 2023).
cervical carcinoma (5 papers, 2016 to 2025). A carcinoma arising from either the exocervical squamous epithelium or the endocervical glandular epithelium. "This suggests that Rad21 involves the development of cervical cancer possibly by participating in the regulation of cell cycle and the nuclear output of the tumor suppressor gene via XPO1." (PMID 29797792, 2018). "The Rad21 gene involves the development of cervical cancer possibly by participating in the regulation of cell cycle and the nuclear output of the tumor suppressor gene by XPO1." (PMID 29797792, 2018). "We generated Rad21 ChIP-seq for 293 T cells (kidney), B-cells (lymphocytes), human skin fibroblast cells, RPE (retinal pigmented epithelium) cells, and HeLa cells (cervical cancer)." (PMID 35680859, 2022). "A comprehensive understanding of the molecular interactive mechanism between Rad21 and XPO1 in nuclear transport will lead to better miRNA therapeutic strategies for cervical cancer." (PMID 29797792, 2018). "In the correlation network among RAD21, SMC3, and MXI1, the three factors were tightly connected with one another in HeLa-S3 cervical carcinoma cells." (PMID 27139377, 2016). "RAD21 was significantly overexpressed in cervical intraepithelial neoplasia III and cervical cancer and involved in the regulation of cell cycle and RNA transportation, promoting cervical cancer progression." (PMID 35860572, 2022).
Ewing sarcoma (5 papers, 2022 to 2025). A small round cell tumor that lacks morphologic, immunohistochemical, and electron microscopic evidence of neuroectodermal differentiation. "In addition, a series of experiments using mouse and human cell models for Ewing sarcoma associated the gain of chromosome 8 with the up-regulation of the RAD21 and MYC genes that reside on that chromosome." (PMID 36859339, 2023). "Furthermore, the association of STAG2-mutations with trisomy 8 is intriguing considering recent findings suggesting that RAD21 is the driver of chromosome 8 gain to mitigate replication stress in Ewing sarcoma, a disease characterized by frequent STAG2 mutations." (PMID 39033241, 2024). "Human Ewing sarcoma cells carrying the fusion oncogene EWS-FLI1 frequently exhibit adaptive amplification of the cohesin subunit RAD21." (PMID 40571846, 2025). "Recent breakthroughs in experimental models for Ewing sarcoma in mice and human cells have found a partial contribution in the Rad21 and Myc genes for the selection of chromosome 8 trisomy." (PMID 36859339, 2023). "In Ewing sarcoma A673 cells, non-CTCF cohesin sites were detected with an antibody against SMC1, but they showed little enrichment for RAD21, STAG1 or STAG2." (PMID 36424654, 2022).
hepatocellular carcinoma (5 papers, 2017 to 2022). A malignant tumor that arises from hepatocytes. "Recently, Cai et al11 found that nuclear Rad21 was increased in hepatocellular carcinoma tissues compared to adjacent nontumor tissues, and higher Rad21 levels are associated with shorter overall survive of hepatocellular carcinoma patients." (PMID 29797792, 2018). "Low expression of miR-320b resulted in a weakened inhibition of RAD21 in hepatocellular carcinoma treated with ionizing radiation, resulting in the reduction of therapy-induced DNA damage." (PMID 35592674, 2022). "RAD21 expression was upregulated within ionizing radiation-insensitive hepatocellular carcinoma tissues, which led to reduced cell sensitivity to therapy by attenuating ionizing radiation treatment-induced DNA damage." (PMID 35860572, 2022).
non-small cell lung carcinoma (5 papers, 2022 to 2025). A group of at least three distinct histological types of lung cancer, including non-small cell squamous cell carcinoma, adenocarcinoma, and large cell carcinoma. "The upregulation of RAD21 is also found to predict poor survival of non-small-cell lung cancer patients." (PMID 35468892, 2022). "In non-small cell lung cancer, high expression of RAD21 mediated cisplatin resistance by enhancing DNA damage repair." (PMID 35860572, 2022). "Furthermore, high RAD21 expression conferred poor survival in patients with non-small cell lung cancer, especially in stages II–III." (PMID 35860572, 2022).
breast tumors (4 papers, 2013 to 2022). "Median telomeric content in samples with alterations in RAD21 was significantly higher than in WT for breast tumors, lung adenocarcinoma, and prostate acinar adenocarcinoma (p<0.0001 for all)." (PMID 35227290, 2022). "RAD21 is amplified in 13.9% (67/482 tumors) of breast tumors evaluated, while it is amplified in 18.0% (57/316 tumors) of ovarian tumors." (PMID 23962039, 2013). "Specifically, all three over-expressed key regulators in breast tumors, GATA3, E2F1 and RAD21, showed connection with these two lincRNAs." (PMID 27897201, 2016).
endometrial cancer (4 papers, 2013 to 2022). Primary or metastatic malignant neoplasm involving the endometrium (mucous membrane that lines the endometrial cavity). "Previous studies have shown that both RAD21 and CTCF are deregulated or aberrantly expressed in endometrial cancer." (PMID 25487306, 2015).
lung cancer (4 papers, 2018 to 2024). A malignant neoplasm involving the lung. "In lung cancer, a recent study indicated that higher levels of RAD21 in NSCLC tissues are associated with poorer survival of patients with NSCLC12." (PMID 38378967, 2024). "Our results suggest that RAD21 promotes lung cancer cell tumorigenicity through activation of the PI3K pathway." (PMID 38378967, 2024). "RAD21 knock down shows resistance to DNA-damaging chemotherapeutic drugs in vitro, and its increased expression is evident in poorly differentiated lung cancers due to its contribution to the regulation of the cell cycle." (PMID 36142846, 2022). "RAD21 facilitates PI3K gene transcription, and the PI3K pathway is an important regulator in lung cancer tumorigenesis." (PMID 38378967, 2024). "To date, its relationship with RAD21 has not been explored, and this study, to the best of our knowledge, demonstrates that RAD21 mediates its oncogenic effects via the PI3K pathway in lung cancer." (PMID 38378967, 2024).
melanoma (4 papers, 2020 to 2025). A malignant, usually aggressive tumor composed of atypical, neoplastic melanocytes. "As previously stated, CHK1 contributes to the DDR, and in melanomas, increased RAD21 expression associated with an increased sensitivity to CHK1i." (PMID 32859084, 2020). "We evaluated RAD21 expression in 2 independent clinical immune checkpoint blockade (ICB) cohorts with advanced melanoma (GSE91061 and GSE168204)." (PMID 36201246, 2022). "Arm-level gene alterations in chromosome 8q21-24, where RAD21, NBN, and MYC are located, were found in approximately one fourth of mucosal melanomas." (PMID 39823560, 2025).
myeloid leukemia (4 papers, 2015 to 2020). A clonal proliferation of myeloid cells and their precursors in the bone marrow, peripheral blood, and spleen. "The here-identified, novel role of Rad21/cohesin-mediated NF-κB signaling in impairing HSC self-renewal during aging could also be relevant for the selection of cohesin mutations in human aging and during early stage of myeloid leukemia." (PMID 30530755, 2019).
oral squamous cell carcinoma (4 papers, 2012 to 2022). "RAD21 is a critical gene in double-strand DNA repair and mitotic growth and gene overexpression was recently shown to be involved in invasion and metastasis in oral squamous cell carcinoma." (PMID 22905093, 2012).
Cognitive impairment (3 papers, 2020 to 2026). Abnormal cognition is characterized by deficits in thinking, reasoning, or remembering. "The cognitive impairment observed is generally more severe than in patients with mutations in the SMC1A, SMC3, BRD4, and RAD21 genes." (PMID 38673696, 2024). "Three genes (TRPS1, RAD21, and EXT1) are considered responsible for the most common clinical features, which include facial dysmorphism, ectodermal and skeletal anomalies, osteochondromas, and cognitive impairment." (PMID 41683676, 2026). "Prenatal microcephaly has been demonstrated to be a predictor of more severe cognitive impairment in CdLS in the pre-molecular era but this does not hold for RAD21 patients." (PMID 32193685, 2020).
developmental delay (3 papers, 2018 to 2025). "RAD21 mutations are implicated in a spectrum of cohesinopathies beyond CdLS, often presenting with developmental delay, multiorgan involvement, and sometimes immune dysregulation." (PMID 41226818, 2025). "Mutations in RAD21 (double-strand-break repair protein rad21 homolog, 8q24.11) have been rarely observed in association with a non-classic CDLS phenotype featuring structural anomalies consistent with CLDS but only minor to mild developmental delay." (PMID 33478103, 2021).
myelodysplastic syndrome (3 papers, 2019 to 2024). A clonal hematopoietic disorder characterized by dysplasia and ineffective hematopoiesis in one or more of the hematopoietic cell lines. "In myelodysplastic syndromes (MDS), a heterogeneous group of clonal hematopoietic disorders characterized by cytopenia, ineffective hematopoiesis and an increased risk of progression to AML, RAD21, STAG2, and SMC1A are the most frequently mutated genes (∼15%) and are associated with poor survival." (PMID 30873408, 2019).
Roberts syndrome (3 papers, 2013 to 2021). "Additionally, mutations in three Cohesin subunits (SMC1α, SMC3, RAD21) and in one Cohesin-interacting protein (NIPBL) have been found causal for CdLS, whereas mutations in ESCO2 are responsible for Roberts syndrome/SC Phocomelia (OMIM# 269000)." (PMID 33263776, 2021).
brain tumor (2 papers, 2020 to 2022). "We found that a reduction in Rad21 levels prevents ALT-associated phenotypes in zebrafish brain tumors and triggers an increase in tert expression." (PMID 33266037, 2020). "Another important finding of our study is the further increase of DSBs in Rad21 haploinsufficient brain tumors compared to ALT brain tumors." (PMID 33266037, 2020). "To generate a brain tumor model with reduced levels of rad21, we used the rad21ahi2529Tg/+ line, created by retroviral-mediated insertional mutagenesis with the insertion mapped in the first intron of the rad21a gene, in chromosome 16." (PMID 33266037, 2020). "Here we use a zebrafish juvenile brain tumor model that progressively develops ALT to test whether haploinsufficiency for Rad21, a member of the cohesin complex, may impair ALT development." (PMID 33266037, 2020). "In this study, we used a model of progressive juvenile brain tumor that develops ALT as primary telomere maintenance mechanism to test whether haploinsufficiency for Rad21 may modify ALT development." (PMID 33266037, 2020). "Remarkably, we found that while an accumulation of γH2AX foci was present at telomeres (telomere induced foci, TIFs) in RAS tumors, rad21;RAS brain tumor cells showed an even greater number of γH2AX-positive TIFs." (PMID 33266037, 2020). "When we measured telomerase activity using TRAP assay, we found that rad21;RAS brain tumors showed a trend versus telomerase reactivation." (PMID 33266037, 2020). "We assessed DNA damage by measuring the level of the DNA damage marker γH2AX, and the occurrence of HR using immunofluorescence for the DSB repair protein RAD51, both combined with telomeric FISH, in RAS and rad21;RAS brain tumors." (PMID 33266037, 2020). "Our data on the increase of DSBs without a corresponding increase in rad51 loading in Rad21+/−;RAS brain tumors in which ALT is prevented, suggest that the reduction of rad21 levels prevent signalling to wapl and separase for rad51 loading." (PMID 33266037, 2020). "RAD21 has been shown to be important for telomere end protection and its depletion prevented alternative lengthening of telomeres (ALT) in zebrafish brain tumor cells in vivo." (PMID 35227290, 2022). "Therefore, we checked the expression of tert, the catalytic subunit of telomerase, in rad21;RAS brain tumors using qPCR." (PMID 33266037, 2020). "Here we used a zebrafish model of brain tumor, which uses alternative lengthening of telomeres (ALT) as primary telomere maintenance mechanism to test whether haploinsufficiency for Rad21, a member of the cohesin ring, affects ALT development." (PMID 33266037, 2020). "RNA dot blot analysis on total RNA extracted from control, RAS or rad21;RAS brain samples showed that the levels of TERRA in RAS Rad21+/− tumors were similar to those found in control brain and in telomerase+ HeLa cells, much lower than those present in ALT brain tumors (RAS) and U2OS cells." (PMID 33266037, 2020). "To study whether a reduction in rad21a expression affects ALT development, we performed an analysis of TMM in RAS and rad21;RAS brain tumors." (PMID 33266037, 2020). "In this case, the increase of DSB found in rad21 haploinsufficient brain tumors may not promote ALT because the reduction of rad21a levels impairs cohesion and does not provide the spatial proximity required for recombination." (PMID 33266037, 2020).
breast invasive ductal carcinoma (2 papers, 2011 to 2022). "In total, RAD21 alterations were associated with a worse mOS in the total breast invasive ductal carcinoma cohort, with the strongest effect observed in the HER2 positive subset." (PMID 35227290, 2022). "Our results are in line with this finding, where patients with RAD21 altered breast invasive ductal carcinoma had significantly worse median overall survival compared to their WT counterparts." (PMID 35227290, 2022).
holoprosencephaly (2 papers, 2020 to 2023). Holoprosencephaly (HPE) is a complex brain malformation resulting from incomplete cleavage of the prosencephalon, occurring between the 18th and 28th day of gestation, and affecting both the forebrain and face, which results in neurological manifestations and facial anomalies of variable severity. "Recently, a case of holoprosencephaly associated with the RAD21 loss-of-function variant was described." (PMID 36672860, 2023). "Loss of function-variants in cohesin genes including RAD21 were found in individuals with holoprosencephaly of whom some demonstrated CdLS features as well." (PMID 32193685, 2020). "Other authors reported holoprosencephaly associated with variants in STAG2, SMC1A, SMC3 and RAD21." (PMID 36672860, 2023). "The prevalence of holoprosencephaly spectrum in RAD21-CdLS must remain uncertain as brain MRIs are typically not indicated in individuals with CdLS due to the burden of the procedure and lack of consequences of findings for care." (PMID 32193685, 2020).
intrahepatic cholangiocarcinoma (2 papers, 2020 to 2022). A carcinoma that arises from the intrahepatic bile duct epithelium in any site of the intrahepatic biliary tree. "Surprisingly, a recent case report demonstrated that a patient with metastatic intrahepatic cholangiocarcinoma carrying a BRCA1-associated protein 1 (BAP1) mutation and RAD21 amplification benefited from PARP inhibitor treatment." (PMID 35860572, 2022).
liver cancer (2 papers, 2020 to 2021). An epithelial or non-epithelial malignant neoplasm that arises from the liver. "The association between ARID1A/BRG1 and CTCF/RAD21 was affirmed in human liver cancer cell lines in vivo." (PMID 34689165, 2021). "In order to determine the biological interaction network of CENPM in liver cancer, we used the network in the "Network" tab in cBioPortal, showing the 50 most frequently changed neighbor genes in CENPM, and the most common change was RAD21 (18.3%)." (PMID 32863765, 2020).